IL10 (interleukin 10)
Diseases named in the same sentence as IL10 in open-access papers (continued):
Sharing a sentence is not in itself a finding about the gene and the disease.
tumor (continued). "Moreover, the production and secretion of anti-inflammatory cytokines such as tumor growth factor-β (TGF-β) and IL-10 by immunosuppressive immune cells can help inhibit anti-tumor responses in PC and have a poor prognosis in these patients." (PMID 34868907, 2021). "Moreover, miRNA-214 promotes the secretion of IL-10 in Tregs, which encourages tumor growth in vivo." (PMID 34830787, 2021). "This suggests that in addition to recognizing and removing cancer cells and presenting tumor antigen to T cells, L2pB1 cells may contribute to limiting tumor metastases by regulating inflammation through PD-L2 and IL-10 expression." (PMID 34630396, 2021). "Second, TGF-β and IL-10, which are closely related to tumor cell invasion, are increased in the exosomes of metastatic small cell lung cancer cells, and this activates SMAD, phosphatidylinositol 3-kinase (PI3K)/AKT, BRAF-MAPK, and other signaling pathways, thereby promoting tumor metastasis." (PMID 34485600, 2021). "M1 macrophages mainly participate in positive immune responses such as immune surveillance and inhibition of tumor growth, whereas M2 macrophages mainly secrete inhibitory cytokines (such as IL-10 and TGF-β) to down-regulate the immune response, thereby promoting tumor growth." (PMID 35126464, 2021). "Further, as previously reported, BTLA blockade decreased the production of the immunosuppressive and tumor-promoting cytokine IL-10 by B cells, suggesting that targeting BTLA signaling may restore, at least in part, NK cell immune competence." (PMID 33917094, 2021). "After determining the critical role CD8+T cells in the antitumor effect, we further examined whether IL-10, hTERT or the combination treatment could modulate their density in the tumor microenvironment." (PMID 33717103, 2021). "The oncolytic vaccinia virus armed with IL-10 treatment contributed to significantly reduced frequencies of antiviral T cells, whereas the frequency of tumor-specific CD8+ T cells was comparable to oncolytic vaccinia virus monotherapy at days 8 and 24 post-infusion." (PMID 33717103, 2021). "As expected, the pro-tumor IL-10 level was significantly lower in the serum of animals from the ‘EVs-Hsp70’ group than in serum of mice from the ‘Untreated’ groups (3.6 ± 0.2 vs 25.5 ± 0.6 pg/mL, p = 0.000001 for B16 and 4.8 ± 0.2 vs 18.4 ± 1.6 pg/mL for CT-26, p = 0.0001)." (PMID 34716378, 2021). "Moreover, IL-10 expression was also increased, with similar expression levels in TC and IC on both tumor regions (mean combined score, TC vs. IC: 8.8 vs. 7.8, p = 0.587 for MIBC; 9.3 vs. 8.3, p = 0.333 for CIS)." (PMID 33672843, 2021). "In various tumor types, IL-10 has been shown to impair CD8+ T-cell function." (PMID 34065010, 2021). "Eosinophils, as TAMs, are also able to infiltrate tumors and influence tumor progression, inhibiting tumor growth by secreting IL-10 and IL-12, or promoting it by secreting growth factors such as epidermal growth factor (EGF) and transforming growth factor-b1 (TGF-b1)." (PMID 34830940, 2021). "AM0010 (also called pegilodecakin) is a modified PEGylated IL-10 that may enhance the anti-tumor immune response by harnessing the immunostimulatory function of IL-10." (PMID 33746989, 2021). "Tregs provide defense against infections and tumor cells, in part by secreting IL-10 and TGF-b." (PMID 34239993, 2021). "Peritoneal IL10 concentration correlates with peritoneal tumor burden in patients with CRC." (PMID 33911154, 2021). "IL-10 increased NK cell activity and inhibited tumor development and metastasis." (PMID 33578830, 2021). "A large amount of evidence indicated crucial roles of IL-10 in the anti-tumor process." (PMID 34497832, 2021). "What's more, it had been reported that IL‐10 could promote tumor progression by promoting NF‐κB‐mediated transcription." (PMID 34545634, 2021). "MARCO expression is induced by tumor-derived supernatant, IL-10, hypoxic conditions and IL-37." (PMID 34572013, 2021).
tumor (continued). "However, more evidence is required to verify its safety to avoid the on-target, off-tumor toxicity in IL-10 CAR-T therapy." (PMID 34392305, 2021). "Downregulation of IL-10 expression by proglumide may explain the mechanism involved with the change in the tumor immune cell signature we observed in the tumors." (PMID 34638432, 2021). "It is known that stimulation and inhibition of IL-10 signaling can prevent tumor growth." (PMID 33628584, 2021). "However, IL-10 was expressed by significantly more tumor-infiltrating CD8+CD103+ TRMs than CD69− T cells (p=0.0239, n=10 tumors) and CD103− TRMs (p=0.0423)." (PMID 33479027, 2021). "M1 macrophages could secrete high levels of proinflammatory cytokines such as TNF-α and low levels of IL-10, which facilitate a robust anti-tumor activity." (PMID 33867819, 2021). "TNF-α, IL-6, IL-10, and TGF-β are secreted by neoplastic cells and tumor-associated macrophages." (PMID 34574650, 2021). "In addition, a decrease in TGF-β and IL-10 in tumor lysates was observed in atovaquone-treated mice with a reduction in tumor Tregs." (PMID 34068008, 2021). "The transition of TAMs into M2 state releases an abundant amount of transforming growth factor TGF-β, epithelial growth factor (EGF), matrix metalloproteinase MMP-2 and MMP-9, and IL-10, thus promoting tumor angiogenesis and invasion, as well as immune-suppressed microenvironment." (PMID 34439380, 2021). "In fact, recombinant PEGylated IL-10 inhibits tumor cell growth in mice." (PMID 33809496, 2021). "IL-10 is an inhibitory cytokine that regulates tumor immune responses." (PMID 32545709, 2020). "In addition, the expression of the toll-like receptor 4 on M2 macrophages promotes a vicious circle, stimulating further IL-10 release by tumor cells and promoting EMT through E-cadherin inhibition and Snail and vimentin upregulation." (PMID 32012917, 2020). "One study reported that serum IL-10 and IL-6 levels correlated with tumor size in HCC patients." (PMID 32443546, 2020). "Macrophages in the tumor microenvironment also secrete IL-10." (PMID 33330068, 2020). "Furthermore, in tumor tissue supernatants from Rag2−/− mice, IFNγ and IL-17A were significantly increased, while IL-10 was significantly decreased." (PMID 33042110, 2020). "Anyway, whether IL-10 is a tumour promoting agent or inhibitor still needs further studies to elucidate." (PMID 32760201, 2020). "IL-10 from TAM in GBM have the ability to promote tumor growth in vitro via JAK2/STAT3 pathway." (PMID 32765498, 2020). "Furthermore, immunofluorescent staining also demonstrated significantly increased IL-12 expression and decreased IL-10 expression in the tumour tissues of HSD-fed mice." (PMID 32265505, 2020). "Then, MDSCs circulate in the blood and spleen and eventually home to tumor sites, in which factors such as interleukin (IL-10) and transforming growth factor beta (TGFβ) secreted by MDSCs accelerate tumor growth by impeding antitumor activity and promoting suppressive cell differentiation." (PMID 32325683, 2020). "On top of their discrete suppressive contributions, both IL-10- and IL-35-secreting Tregs can synergize to mastermind the conversion of activated Tconv cells into immunomodulatory IL-35-producing Tconv cells capable of thwarting anti-tumor immunity." (PMID 33375291, 2020). "For example, many solid tumours (e.g., pancreatic, colon) are largely devoid of CTLs at the core of the tumour owing to the presence of TAMs, which secrete cytokines (interleukin-10 (IL10), TGFβ) that inhibit DC maturation and dampen effector T cell activity and infiltration." (PMID 32825277, 2020). "Additionally, tumor growth increases the recruitment of CD4+ regulatory T cells that secrete IL-10 and TGF-β and suppress effector CD8+ T cell responses." (PMID 31938023, 2020). "Moreover, adding anti-PD1 to the RT plus vaccine group led to the recovery of the IL-10 levels in the single tumor cells." (PMID 32733437, 2020).
tumor (continued). "Therefore, in our experimental model, IFN-γ would favor tumor growth and progression and, on the other hand, IL-10 would participate in the antitumor immune response." (PMID 33312693, 2020). "The study also indicated that DC recruitment at the position of tumor cell inoculation could be depressed by IL-10, thus preventing DCs' exposure to tumor antigens." (PMID 32391256, 2020). "In our experience, TME changed towards a more inflamed environment, evidenced by the increase of cytokines like CXCL10 and CCL2, and the decrease of immunosuppressive molecules (like FoxP3 and Nos2), and molecules that promote tumor growth and invasiveness (like IL10 and TGFβ)." (PMID 32064039, 2020). "Moreover, the tumor microenvironment is engulfed of immune suppressive cytokines such as IL-6 and IL-10 as well as T-regulatory cells whose migration nearby tumor cells contribute to enhance the evasion from the immune system control." (PMID 32751327, 2020). "Activated MDSCs suppress anti-tumor immunity by various mechanisms, including activation of inducible NO synthase and arginase-1 and induction of anti-inflammatory cytokines such as IL-10." (PMID 32320454, 2020). "IL-10 in the tumor microenvironment can inhibit the host's antitumor immune response." (PMID 32832569, 2020). "Therefore, effective transportation of IL10 gene to the tumor site and its continuous local expression is the focus of this study." (PMID 32742480, 2020). "Still, targeting HMGB1 or histone-deacetylase 11 by specific inhibitors could also provide an avenue to inhibit MDSC expansion and limit IL-10 production and thus enhance anti-tumour/infection immune responses." (PMID 32931721, 2020). "Similarly, human U937 monocytic cells, which lack endogenous IgE bound on IgE Fc receptors prior to stimulation with anti-tumour IgE, also upregulated TNFα, MCP-1, and IL-10 expression with MOv18 IgE-dependent cytotoxic killing (ADCC) of tumour cells." (PMID 33203088, 2020). "However, IL-10 was also shown to inhibit tumor-induced angiogenesis, enhance the production of NO, and increase tumor cell line immunogenicity in some preclinical models." (PMID 33042814, 2020). "IL-10-producing “regulatory” B (B10) cells have been shown to be functional in murine models of tolerance, in preventing chronic inflammation and in curbing anti-tumor immune responses." (PMID 33569063, 2020). "Moreover, activation of M2 macrophages due to factors like IL-13, IL-10, IL-4, and glucocorticoid, promote tumor growth by secreting high levels of IL-10 and low levels of IL-12." (PMID 33133086, 2020). "Furthermore, activation of TLR4 signaling on M2-polarized TAMs stimulates IL-10 release, thus promoting cancer progression, especially in the advanced stages of metastatic growth of the tumor." (PMID 32283687, 2020). "In order to characterize the M-406/CBi/L model with respect to cytokines involved in the different phases of tumor immunoediting, it was evaluated the concentration of Th-1 (IFN-γ, IL-2) and Th-2 (IL-10, IL-4) cytokines in serum from tumor bearing animals during EL, EQ and ES phases." (PMID 33312693, 2020). "Moreover, through the secretion of interleukin 10 (IL-10) and transforming growth factor beta (TGF-β), GSCs are able to suppress the tumor-associated microglia, generating an M2 immunosuppressive phenotype." (PMID 33375034, 2020). "Furthermore, m-MDSCs can indirectly suppress anti-tumor immunity, through the production of TGF-β and IL-10 cytokines, which inhibit anti-tumor TILs, generate regulatory T-cells (Tregs) in the tumor and induce DCs into a regulatory phenotype." (PMID 32656079, 2020). "In immunotherapy it is hypothesized that, due to the systemic inflammation initiated by the tumor itself, the increased infiltration of neutrophils promotes cancer progression via secreting interleukin-10 (IL-10), tumor necrosis factor α (TNF-α), and VEGF." (PMID 33272262, 2020).
tumor (continued). "Its application to the analysis of the joint behavior of IFN-γ, IL-2, IL-10 and IL-4 showed that the differences observed in the growth of M-406 tumor could be explained by the first two main components." (PMID 33312693, 2020). "Moreover, the correlation on patients’ survival was not only found for IL-10 within the tumor but also for the unaltered mucosa close to the resection margin representing a local immunological field effect." (PMID 32298379, 2020). "In addition, significantly higher numbers of tumor-associated macrophages are observed in EBV+ HL as compared to EBV-negative HL, which can also produce IL10." (PMID 31963774, 2020). "IL-10 itself is upregulated in HCC TME, defining risk of progression after tumor resection." (PMID 33718121, 2020). "The transient invigoration of exhausted CD8+ T cells to potent tumor-reactive cells has been achieved through the combination of anti-PD-1 therapy with PEGylated IL-10, leading to the expansion of a rare population of LAG-3+ PD-1+ CD8+ T cells that positively correlates with clinical response." (PMID 33193370, 2020). "Cancer cells can also secrete IL-10, as can tumor-infiltrating macrophages." (PMID 32283655, 2020). "MTDH and IL-10 expression were observed in the cytoplasm of the tumor sections." (PMID 33003428, 2020). "Consistent with our findings, it has been shown that IL-10R signaling is involved in overstimulation of STAT3, enabling tumor cells to grow uncontrollably and to become resistant to the induction of apoptosis, confirming the link demonstrated here between IL-10 and STAT3." (PMID 32222879, 2020). "For instance, a significant decrease in IL-10, a key cytokine released by tumor cells to suppress the host immune function by inhibition of dendritic cell differentiation and maturation in vitro, was observed following combination treatment of 1,4-dihydroxy quininib with Bevacizumab." (PMID 33008336, 2020). "These cells establish a favorable environment for tumor development by releasing cytokines (IL-6, IL-10 and TGF-β), metalloproteinases (MMP3 and MMP9) and growth factors (HGF, EGF, CTGF and IGF-1), leading to immunomodulation, angiogenesis, invasion, proliferation and tumor cell survival." (PMID 32899449, 2020). "In conclusion, increased phosphorylation of STAT3 in tumour‐conditioned microglia upregulates the expression of IL‐10 and IL‐6 in an mTOR‐dependent fashion with a concomitant reduction in expression of IL‐12 mediated by reduced phosphorylation and nuclear translocation of NF‐κB." (PMID 32567735, 2020). "Interestingly, it has been demonstrated that PPAR beta/delta activation in tumor-infiltrating myeloid cells stimulates cancer cell invasion and facilitates tumor angiogenesis via an Interleukin 10- (IL10-) dependent manner." (PMID 32855630, 2020). "In addition, the increased production of IL-10 will block the effect of specific T lymphocytes on tumor cells, and NCTD inhibits the production of IL-10 in PBMC induced by PHA (phytohemagglutinin)." (PMID 32514288, 2020). "While normal NKTs have anti-tumor effects, IL-6+ IL-10+ NKT cells lose these functions." (PMID 32178454, 2020). "Moreover, compared to TAMs from WT tumor-bearing mice, those from Ubr5−/− tumor-bearing mice exhibited higher levels of M1 macrophage markers (e.g., il12a, Ccr2) and lower levels of M2 markers (e.g., Cx3cr1, il10)." (PMID 33293516, 2020). "It is commonly known that monocytes/macrophages contribute directly to tumor progression by releasing factors that promote angiogenesis and metastasis, and certain types of activated macrophages have been shown to produce IL-10 at inflammatory sites." (PMID 33614473, 2020). "In colorectal cancer, IL-6 was shown to stimulate IL-10 production by tumor cells." (PMID 33042814, 2020). "How to transport IL10 to the tumor microenvironment is an urgent problem to be solved." (PMID 32742480, 2020). "The potential mechanism of IL-10 in tumor immunity needs further investigation." (PMID 32348468, 2020).
tumor (continued). "In addition, tumor cells in pancreatic cancer tend to release IL-10, which induces an immunosuppressive effect by limiting the activity of T-lymphocytes." (PMID 32488850, 2020). "Moreover, M2-TAMs produced tumor-promoting cytokines, such as interleukin (IL)-6 and IL-10, which suppress cytotoxic TIL." (PMID 32756500, 2020). "IFN-γ and IL-6 are proinflammatory cytokines and their elevated concentration in ICI responders could reflect spontaneous anti-tumor immune response, however, the explanation for higher IL-10 levels is much more obscure." (PMID 32992737, 2020). "Adoptive transfer of these Bregs into B-cell-deficient mice promoted tumor growth, which was not mediated by IL-10 secretion." (PMID 33193391, 2020). "In contrast, the presence of NCM within the tumor and the subsequent recruitment of neutrophils driven by them, leads to the suppression of T cell-mediated anti-tumor immunity due to the release of immunosuppressive IL10 in a mouse model of colorectal cancer." (PMID 32824655, 2020). "Moreover, we and others observed that IL-10-treated primary human MΦ adopted an iron-releasing phenotype with consequences for tumor cell proliferation in vitro." (PMID 32188161, 2020). "M1-type macrophages encourage inflammation that help to clear infection and may inhibit tumor cell growth, whereas M2-type macrophages decrease inflammation through producing an anti-inflammatory cytokine IL-10 and improve tissue repair." (PMID 32308723, 2020). "However, even intermittent enterotoxigenic B. fragilis colonization as short as 2 weeks appears to be sufficient to induce tumor formation, so it is possible that bft expression occurred at an earlier time point in the ApcMinΔ850/+;Il10−/− model." (PMID 31937674, 2020). "IL‐10, an immuno‐regulatory cytokine, is well known for its immunosuppressive function and contributes to the maintenance of an immunosuppressive milieu within the tumour environment." (PMID 33037771, 2020). "Both TGF-β and IL-10 cytokines are known to be suppressive cytokines mainly released by Tregs, which may directly suppress effector T cells in the tumor microenvironment." (PMID 32733437, 2020). "Importantly, M2-like TAMs release immunosuppressive cytokines, such as IL-10 and TGFb, and express programmed cell death 1 (PD-L1) to inhibit T cell function in the tumor microenvironment." (PMID 32708944, 2020). "Furthermore, they have shown that Withaferin A can prevent the increased production of IL-10 by MDSCs upon cross-talking with MΦ, therefore inhibiting pro-tumour immune responses, namely type 2 immune responses." (PMID 32931721, 2020). "The levels of IL-10 are significantly increased in both the tumor tissue and serum of GC patients." (PMID 32268527, 2020). "Moreover, rlipoE7m plus POCpG/DOTAP combined reduced the number of tumor-infiltrating regulatory T cells dramatically due to downregulation of IL-10 production by DCs." (PMID 32231003, 2020). "Tumor cells produce immunosuppressive cytokines (e.g., IL-10, TGF-β, PGE2), recruit Tregs, activate negative regulatory pathways (e.g., PD-1/PD-L1, CD80/CTLA4) or express immunomodulatory molecules (e.g., IDO), thus establishing an immunosuppressive microenvironment." (PMID 32054102, 2020). "Taking into account the potential role of IL-10 and IL-17 in tumor promotion, these results may explain the differences in the treatment outcome in both models." (PMID 33312174, 2020). "Furthermore, fruti induced necrosis and apoptosis, increased N-acetyl-β-D-glucosaminidase and TNF-α levels and reduced IL-10 and Vegf levels in tumor tissue." (PMID 33020521, 2020). "Additionally, IL-10 and TGFβ are reported as key mediators that limit antitumor immunity and promote tumor progression." (PMID 32850861, 2020). "These Tregs in turn secret IL‐10, which promotes tumour growth." (PMID 33169503, 2020).